MAS1 (MAS1 proto-oncogene, G protein-coupled receptor)
Description:
G protein-coupled receptor that plays key roles in the renin-angiotensin system (RAS) specifically in the protective, counter-regulatory arm of the RAS. Receptor mainly stimulated by angiotensin 1-7, which is a bioactive metabolite of the angiotensin produced by ACE2. Activation promotes nitric oxide via PI3K/Akt-eNOS pathway. Modulates also the MAPK, ERK1/2, and NF-kappa-B signaling. Positive regulation of AGTR1 levels occurs through activation of the G proteins GNA11 and GNAQ, and stimulation of the protein kinase C signaling cascade. The antagonist effect on AGTR1 function is probably due to AGTR1 being physically altered by MAS1. Acts as functional receptor for CXCL17 and induces chemotactic movement.
Synonyms: MAS; MGRA
Tractability: Small molecule: it belongs to a druggable protein family. Antibody: UniProt places it where antibodies can reach, with high confidence; its Gene Ontology location is reachable by antibodies, with high confidence; UniProt predicts a signal peptide or a membrane-spanning region. PROTAC: a small molecule that binds it is known. Other modalities: a drug acting on it is in phase 2 or 3 trials.
Target class: Family A G protein-coupled receptor; Membrane receptor
Gene: Protein-coding gene on chromosome 6 (159,890,988 to 159,917,447, forward strand). Ensembl gene ENSG00000130368.
Subcellular location: Cell membrane
Pathways (Reactome):
Signal Transduction: Peptide ligand-binding receptors
Gene Ontology:
Molecular function: C-C chemokine receptor activity; G protein-coupled receptor activity; protein binding; angiotensin receptor activity; angiotensin type II receptor activity; peptide binding
Biological process: cell migration; chemokine-mediated signaling pathway; phospholipase C-activating angiotensin-activated signaling pathway; G protein-coupled receptor signaling pathway
Cellular component: plasma membrane; membrane
Genetic constraint (gnomAD): Loss-of-function variants: 0 observed, 0.29 expected, observed/expected ratio (o/e) 0, 90% interval 0 to 1.87. That is too few expected variants to judge how well the gene tolerates losing a copy. Missense variants: 387 observed, 430.39 expected, observed/expected ratio (o/e) 0.9, 90% interval 0.83 to 0.98. Synonymous variants: 163 observed, 172.72 expected, observed/expected ratio (o/e) 0.94, 90% interval 0.83 to 1.08.
Homologues: Orthologues: chimpanzee MAS1 (99% identical), macaque MAS1 (98% identical), rat Mas1 (91% identical), dog MAS1 (90% identical), mouse Mas1 (90% identical), guinea pig MAS1 (89% identical), rabbit MAS1 (87% identical), pig MAS1 (85% identical). Paralogues in human: MRGPRX2 (33% identical), MRGPRX4 (33% identical), MRGPRX1 (32% identical), MRGPRX3 (31% identical), MRGPRD (30% identical), MAS1L (30% identical), MRGPRF (29% identical), MRGPRE (24% identical), MRGPRG (22% identical), GPR152 (20% identical).